OOSP1 (oocyte secreted protein 1)
Description:
May be involved in cell differentiation.
Gene: Protein-coding gene on chromosome 11 (59,938,432 to 59,957,480, forward strand). Ensembl gene ENSG00000284873.
Subcellular location: Secreted
Homologues: Orthologues: macaque OOSP1 (78% identical), mouse Oosp1 (38% identical). Paralogues in human: OOSP2 (21% identical), PLAC1 (21% identical).